DPP4 (dipeptidyl peptidase 4)
Diseases named in the same sentence as DPP4 in open-access papers (continued):
Sharing a sentence is not in itself a finding about the gene and the disease.
type 2 diabetes (continued). "This cohort study compares the incidence of atrial fibrillation in patients with type 2 diabetes associated with use of sodium-glucose cotransporter-2 inhibitors with dipeptidyl peptidase-4 inhibitors or glucagonlike peptide-1 receptor agonists." (PMID 36219443, 2022). "Rates of major adverse cardiovascular events, heart failure hospitalisation and all-cause mortality in patients with type 2 diabetes dispensed sodium glucose Cotransporter-2 inhibitors versus dipeptidyl Peptidase-4 inhibitors, stratified by frailty status." (PMID 35903329, 2022). "We propose that impairments in DPP4 control of post-OGTT insulin responses are part of molecular mechanisms underlying early metabolic disturbances associated with type 2 diabetes." (PMID 35190847, 2022). "Other studies have shown that DPP4 genetic polymorphisms in type 2 diabetes are associated with serum lipid levels, with an allele mutation of A to G in rs3788979 being associated with reduced ApoB level." (PMID 35190847, 2022). "Recent studies have suggested that dipeptidyl peptidase-4 inhibitors (DPP4-is), an incretin-based drug for type 2 diabetes, as possible predisposing agents of BP." (PMID 33573656, 2021). "The advantage of dipeptidyl peptidase-4 (DPP-4) inhibitors is their lower risk of inducing hypoglycemia among patients with type 2 diabetes." (PMID 34697593, 2021). "SGLT2 inhibitors such as DN and dipeptidyl peptidase-4 (DPP-4) inhibitors like SN is potentially beneficial in achieving glycemic control without the risk of hypoglycemia or weight gain treatment of type 2 diabetes." (PMID 33345632, 2021). "A meta-analysis of 28 clinical trials enrolling more than 21,000 patients with type 2 diabetes also showed that DPP-4 inhibitors reduced fracture risk compared to placebo and other antidiabetic treatments." (PMID 34205264, 2021). "Despite a similar mechanism of action underlying their glucose-lowering effects in type 2 diabetes, dipeptidyl peptidase-4 (DPP-4) inhibitors have diverse molecular structures, raising the prospect of agent-specific, glucose-independent actions." (PMID 32796688, 2020). "Although obesity is being an important risk factor for type 2 diabetes and DPP4 being a protease, the association between circulating DPP4 activity and obesity remains debatable." (PMID 33312197, 2020). "Sitagliptin, an inhibitor of the dipeptidyl peptidase IV (DPP4), has been implicated in the regulation of type 2 diabetes." (PMID 32774687, 2020). "Of note, DPP4 inhibitors treatment was associated with worse outcomes in 27 patients with type 2 diabetes treated with DPP4 inhibitors than in 49 patients treated with other glucose-lowering drugs." (PMID 33584268, 2020). "The previous study also showed that excessive activity of plasma DPP4 is independently associated with subclinical left ventricular systolic and/or diastolic dysfunction in type 2 diabetes." (PMID 33312197, 2020). "This study was designed to investigate the relationship between plasma DPP4 activity and osteoporosis/osteopenia and fracture risk in newly diagnosed type 2 diabetes." (PMID 33312197, 2020). "Consistent with the previous finding, we extended the better ALT improvements associated with SGLT2 inhibitors vs. DPP4 inhibitors in type 2 diabetes patients with liver disease and 1-year follow-up." (PMID 32050968, 2020). "Elevated plasma DPP4 activity tended to be associated with a higher proportion of osteoporosis/osteopenia and increased the fracture risk in newly diagnosed type 2 diabetes." (PMID 33312197, 2020). "The present study cross-sectionally examined the relationship of plasma DPP4 activities to osteoporosis/osteopenia and fracture risk in newly diagnosed type 2 diabetes." (PMID 33312197, 2020). "Patients with type 2 diabetes have an approximately two-fold risk for acute pancreatitis and a label indicating an acute pancreatitis risk has been added to all DPP-4 inhibitors." (PMID 31275246, 2019).
type 2 diabetes (continued). "In a large cohort of over 140,000 patients with type 2 diabetes, administration of DPP4 inhibitors is associated with an overall 75% increase in the risk of inflammatory bowel disease." (PMID 30972338, 2019). "We compared the effects of SGLT2is with those of dipeptidyl peptidase-4 inhibitors (DPP4is) on the risk of diabetic retinopathy and its progression in people with type 2 diabetes." (PMID 31658289, 2019). "Use of DPP-4 inhibitors has been associated with an at least doubling of the risk of bullous pemphigoid in patients with type 2 diabetes, albeit the absolute risk is again very low." (PMID 31366085, 2019). "In a meta-analysis, sulfonylureas compared with dipeptidyl peptidase 4 inhibitors were associated with a small increased hazard of myocardial infarction and eye disorders in patients with type 2 diabetes." (PMID 30646124, 2018). "In a recent cross-sectional study, higher DPP-4 plasma activity was associated with an increased risk of mild cognitive impairment in elderly patients with type 2 diabetes." (PMID 30597861, 2018). "In this population-based matched cohort of patients with type 2 diabetes, we observed a 14% reduced risk of hospitalization due to HF among new-users of DPP-4 inhibitors, compared to new-users of GLP-1 agonists." (PMID 30016946, 2018). "In this retrospective matched cohort of patients with type 2 diabetes, the use of DPP-4 inhibitors was associated with a reduced risk of HF hospitalization compared to GLP-1 agonists." (PMID 30016946, 2018). "Dipeptidyl peptidase 4 (DPP4), a transmembrane protein, has been identified in human adipose tissue and is considered to be associated with obesity-related type 2 diabetes." (PMID 26881257, 2016). "We therefore performed a meta-analysis of randomized trials to provide a more robust answer regarding the risk of fracture in patients with type 2 diabetes treated with DPP-4 inhibitors." (PMID 27384445, 2016). "HbA1c reduction after use of DPP-4 inhibitors for 3 months was significantly greater in patients with a risk allele for type 2 diabetes (GG -0.4%, CG -0.5%, CC -0.8%, p = 0.02 for rs7754840 and AA -0.4%, AG -0.5%, GG -0.8%, p = 0.01 for rs7756992)." (PMID 27139004, 2016). "The findings are notable in light of the recent clinical trials data that have suggested that DPP-4 inhibitors increase the risk of heart failure hospitalizations in patients with Type 2 diabetes." (PMID 25078106, 2014). "One such example is the dipeptidyl peptidase-IV (DPP4) inhibitor used for treating type 2 diabetes, which is inconclusively implicated in increased susceptibility to acute pancreatitis." (PMID 25671081, 2013). "In this cohort study of 269 064 propensity score–matched adult patients with type 2 diabetes, SGLT2i initiation was associated with a higher prevalence of erythrocytosis compared with dipeptidyl peptidase 4 inhibitors and glucagon-like peptide 1 receptor agonists." (PMID 40549381, 2025). "Dipeptidyl peptidase-4 (DPP-4) inhibitors play a critical role in the management of type 2 diabetes; however, some synthetic drugs may cause adverse effects." (PMID 40509444, 2025). "Additionally, weight neutrality, a common feature of DPP-4 inhibitors, was maintained, which is clinically beneficial for patients with type 2 diabetes and cardiovascular risk, as weight gain can worsen metabolic and cardiovascular profiles." (PMID 39768866, 2024). "In this cohort study of 3 544 383 patients with type 2 diabetes in Taiwan, SGLT2is were associated with a significantly lower risk and lower cumulative incidence of sight-threatening retinopathy than dipeptidyl peptidase-4 inhibitors, pioglitazone, and sulfonylureas." (PMID 38117497, 2023). "While this is a proven and effective strategy in some cases, like the gliptin class of dipeptidyl-peptidase 4 inhibitors for the treatment of type 2 diabetes, it can also cause significant on or off-target side effects that can ultimately prohibit the use of the inhibitor in the clinic." (PMID 38069440, 2023).
type 2 diabetes (continued). "A recent study showed that in patients with GD and type 2 diabetes, DPP4 inhibitors administration was significantly associated with GD exacerbation, which suggested that DPP4 might play a critical role in the pathogenesis of GD." (PMID 37350750, 2023). "In addition, DPP4 also endogenously controls glycemia, which appears as an striking aspect, given that type 2 diabetes has been pointed out as the most important risk factor for SARS-CoV-2 infection and one of the main comorbidities of COVID-19." (PMID 36009573, 2022). "Interestingly, DPP4 activity is increased in patients with type-2 diabetes and the increased risk of type-2 diabetic patients to SARS-CoV-2 infection, suggests that DPP4 class of drugs have the potential to be used as novel therapy." (PMID 33430081, 2021). "This cohort study of older adults with type 2 diabetes examines the association of incident fracture with initiating a sodium-glucose cotransporter–2 inhibitor compared with initiating a dipeptidyl peptidase 4 inhibitor or a glucagon-like peptide 1 receptor agonist." (PMID 34705014, 2021). "Moreover, plasma DPP4 activity is reported to increase in individuals with type 2 diabetes and associate with signs of endothelial dysfunction such as impaired flow-mediated dilatation." (PMID 33312197, 2020). "Interestingly, there is evidence showing that increased DPP4 activity is associated with a high risk of mild cognitive impairment in elderly type 2 diabetes." (PMID 33312197, 2020). "The recent meta-analysis of randomized clinical trials also suggests that treatment with DPP4 inhibitors could be associated with a reduced risk of bone fractures in type 2 diabetes." (PMID 33312197, 2020). "Furthermore, our results revealed that plasma DPP4 activity was also positively related to fracture risk determined with modified FRAX in newly diagnosed type 2 diabetic patients." (PMID 33312197, 2020). "Even though the biological mechanism has not been clear yet, the current findings provide a clue that elevated plasma DPP4 activity could suggest osteoporosis/osteopenia risk and future fracture risk in new onset type 2 diabetes." (PMID 33312197, 2020). "In future studies, the atherogenic properties of lipoprotein subclasses might be considered when employing antidiabetic DPP-4 inhibitors, especially in patients with type-2 diabetes who are at risk for ASCVD or who are undergoing statin treatment." (PMID 31905896, 2019). "In this retrospective matched cohort of patients with type 2 diabetes, the use of DPP-4 inhibitors was associated with a reduced risk of HF hospitalization compared to GLP-1 agonists, although the association was not statistically significant in patients with baseline HF." (PMID 30016946, 2018). "Consequently, three large multicentre clinical trials have recently demonstrated safety with regard to CV outcomes of DPP4 inhibitors in patients with type 2 diabetes at high risk for CV events." (PMID 29040423, 2018). "We found significantly less treatment discontinuation and lower risk of hypoglycemia in patients with type 2 diabetes newly dispensed with DPP-4 inhibitors compared to those initiating NPH insulin, when these agents were used as third-line therapy after metformin and sulfonylurea." (PMID 29713649, 2018). "However, high-level inhibition of DPP-4 was associated with an organ-specific effect on cardiovascular complications in type 2 diabetes." (PMID 26959365, 2016). "Despite their recent clinical introduction, DPP-4 inhibitors, which are associated with a lower risk of drug-induced weight gain and a low incidence of hypoglycemia, now play a central role in the treatment of type 2 diabetes mellitus." (PMID 26550558, 2015). "It is unclear whether dipeptidylpeptidase-4 (DPP-4) inhibition can counteract the impairment of cognitive function and brain injury caused by transient cerebral ischemia in type 2 diabetes." (PMID 25986579, 2015).
type 2 diabetes (continued). "In March 2013, the Food and Drug Administration (FDA) announced that the type 2 diabetic patients treated with the drug classes of incretin mimetics and DPP-4 inhibitors may have a higher risk of pancreatitis and pre-cancerous cellular changes." (PMID 24614606, 2014). "Plasma DPP4 activity was associated with the development of obesity, type 2 diabetes, and type 1 diabetes using animal models; in particular streptozotocin (STZ) is commonly used to induce type 1 and late-phase type 2 diabetic models by selective β-cell destruction in small rodents." (PMID 23853775, 2013). "The results of this study indicate that Type 2 diabetes or insulin resistance associated with obesity is linked to altered insulin signaling pathways, as evidenced by a significant increase in the activities of DPP-4 and PTP1B in the serum by 97% and 118%, respectively, compared to normal rats." (PMID 40376699, 2025). "Is the use of sodium-glucose cotransporter 2 inhibitors (SGLT2is) vs dipeptidyl peptidase 4 inhibitors (DPP4is) associated with reduced total cardiovascular disease (CVD) risks for patients with type 2 diabetes (T2D)?" (PMID 39476235, 2024). "An extremely interesting finding is that the use of SGLT-2 inhibitors in patients suffering from type 2 diabetes (T2DM) is associated with a lower risk of dementia compared to the group of patients taking DPP-4 inhibitors." (PMID 38002034, 2023). "Moreover, dipeptidyl peptidase-4 inhibitors in type 2 diabetes may reduce the risk of autoimmune diseases." (PMID 34745659, 2021). "However, in a separate study involving >100,000 patients with type 2 diabetes, combination therapy of DPP4 inhibitors with metformin resulted in a decreased risk of autoimmune diseases such as rheumatoid arthritis, lupus, psoriasis, multiple sclerosis, and inflammatory bowel disease." (PMID 30972338, 2019). "Use of dipeptidyl peptidase-4 inhibitors (DPP4-i) for the treatment of type 2 diabetes (T2D) has been associated with a possible increase in the risk for heart failure (HF)." (PMID 28183314, 2017). "Therefore, an altered expression of adipose tissue DPP4 could be linked to the development of type 2 diabetes; however the factors that alter the expression of DPP4 are poorly understood." (PMID 26881257, 2016). "Recently the FDA warned that DPP-4 inhibitors for type 2 diabetes may cause severe joint pain." (PMID 27760528, 2016). "Adults with type 2 diabetes initiated on NSAIDs while receiving either SGLT2is or dipeptidyl peptidase-4 inhibitors (DPP4is) were included." (PMID 41545961, 2026). "Repositioning of gliptins, a class of drugs primarily used to treat type 2 diabetes by inhibiting the activity of dipeptidyl peptidase-4 (DPP-4), is being investigated for their potential neuroprotective effects." (PMID 41528544, 2026). "In summary, this real-world cohort study suggests that among patients with type 2 diabetes and bipolar disorder, SGLT-2 inhibitor therapy is associated with a lower risk of suicide-related events compared to DPP-4 inhibitor therapy." (PMID 40567368, 2025). "Beyond its well-established role in type 2 diabetes, where it regulates GLP−1 metabolism and insulin secretion, DPP4 has also been implicated in the development of fibrosis across multiple organs, including the liver, kidney, and skin." (PMID 41334589, 2025). "Specifically, in patients with type II diabetes, inhibiting dipeptidyl peptidase‐4 (DPP4), an enzyme that cleaves X‐proline dipeptides from the N‐terminus of polypeptides, using the DPP4 inhibitor linagliptin, led to changes in numerous urinary peptides." (PMID 39740102, 2025). "Patients with type 2 diabetes who received GLP-1 RAs or dipeptidyl peptidase-4 (DPP-4) inhibitors between 2011 and 2022 were identified." (PMID 40920377, 2025).
type 2 diabetes (continued). "Despite their relatively high cost, DPP-4 inhibitors are frequently prescribed as a third-line add-on therapy for patients with type 2 diabetes who exhibit inadequate glycemic control on combination treatment with metformin and sulfonylureas." (PMID 40771927, 2025). "Common second-line therapies for type 2 diabetes include dipeptidyl peptidase-4 (DPP4) inhibitors, SGLT2 inhibitors, and GLP1 receptor agonists." (PMID 41420258, 2025). "Dipeptidyl Peptidase 4 or DPP-4 inhibitors are a class of drugs called incretins that is FDA approved for the treatment of type 2 diabetes." (PMID 41026724, 2025). "The DPP-4 inhibitor used has been extensively characterized and has been used for treatment of type 2 diabetes since 2006." (PMID 41278011, 2025). "DPP4 inhibitors, commonly used for type 2 diabetes, have shown potential in treating advanced prostate cancer in some contexts by improving overall survival." (PMID 40766751, 2025). "GLP-1 receptor agonists and dipeptidyl peptidase 4 inhibitors have been used for many years in the treatment of type 2 diabetes and metabolic disorders." (PMID 41202140, 2025). "DPP-4 inhibitors are a significant class of compounds used in treating type 2 diabetes; predicting their bioactivity is essential in early drug discovery." (PMID 40761758, 2025). "This trial has investigated the triple combination of metformin, DPP4 inhibitor, and thiazolidinedione in treating drug-naïve type 2 diabetes in Korean patients." (PMID 41155022, 2025). "In a murine model of atherosclerosis and type 2 diabetes, DPP-4 inhibition led to a significant reduction in arterial inflammation as assessed by 18F-FDG uptake." (PMID 40943088, 2025). "In this study, we evaluate the clinical outcomes of SGLT2 inhibitors compared with DPP4 inhibitors in patients with type 2 diabetes and AF in a nationwide population-based cohort." (PMID 39919084, 2025). "One of the most important strategies for the treatment of type 2 diabetes is to reduce or inhibit the activity of dipeptidyl peptidase enzymes (DPP-4) and α-glucosidase." (PMID 40699855, 2025). "Linagliptin (L), a DPP-4 inhibitor used for type 2 diabetes therapy, has putative anti-inflammatory effects." (PMID 40149869, 2025). "In this context, DPP-4 inhibitors are an emerging class of drugs originally used in the treatment of type II diabetes mellitus and recently proven to show protective effects against various disorders." (PMID 40221811, 2025). "Type 2 diabetes is a major cause of CVD, and recently, DPP4 inhibitors have been found to have potentially favorable effects in treating patients with CVDs." (PMID 40904650, 2025). "The primary aim of our study was to evaluate the potential of DPP4 inhibitors (DPP4i) in preventing cognitive decline in mice with type 2 diabetes (T2D), placing special emphasis on gaining insight into the complex molecular mechanisms underlying this action." (PMID 38860903, 2025). "DPP4 inhibitors (DPP4i), primarily employed to regulate glucose levels in type 2 diabetes, demonstrate promising effects on brain function." (PMID 38860903, 2025). "Compared to previous studies on antidiabetic treatments in both PTDM patients and the broader type 2 diabetes population, our findings largely align with established evidence regarding the efficacy of insulin, SGLT2i, and DPP-4 inhibitors." (PMID 40995094, 2025). "Sitagliptin, a DPP-4 inhibitor commonly used in type 2 diabetes, has recently gained attention for its potential anticancer effects." (PMID 41599145, 2025). "In this nationwide population-based cohort study, we found that SGLT2 inhibitors were associated with a lower risk of the composite outcome of hospitalization for HF or mortality compared to DPP4 inhibitors in patients with both type 2 diabetes and AF." (PMID 39919084, 2025).